RNASEH2C (ribonuclease H2 subunit C)
Description:
Non catalytic subunit of RNase H2, an endonuclease that specifically degrades the RNA of RNA:DNA hybrids. Participates in DNA replication, possibly by mediating the removal of lagging-strand Okazaki fragment RNA primers during DNA replication. Mediates the excision of single ribonucleotides from DNA:RNA duplexes.
Synonyms: AGS3; AYP1
Tractability: PROTAC: ubiquitination databases record sites on it; its protein half-life has been measured.
Gene: Protein-coding gene on chromosome 11 (65,714,005 to 65,720,818, reverse strand). Ensembl gene ENSG00000172922.
Subcellular location: Nucleus
Subcellular location (Human Protein Atlas): Nucleoplasm
Gene Ontology:
Molecular function: protein binding
Biological process: RNA catabolic process; mismatch repair
Cellular component: ribonuclease H2 complex; nucleus
Genetic constraint (gnomAD): Loss-of-function variants: 20 observed, 16.19 expected, observed/expected ratio (o/e) 1.24, 90% interval 0.87 to 1.75. The upper end of that interval is the gene's LOEUF score, 1.75, which puts it in group 6 of 6, group 1 being the genes least tolerant of losing a copy. Missense variants: 296 observed, 233.7 expected, observed/expected ratio (o/e) 1.27, 90% interval 1.15 to 1.39. Synonymous variants: 106 observed, 95.61 expected, observed/expected ratio (o/e) 1.11, 90% interval 0.95 to 1.3.
Gene-disease validity (ClinGen):
ClinGen rates the evidence that RNASEH2C causes each of these diseases.
RNASEH2C-related type 1 interferonopathy (autosomal recessive): Definitive. Any type 1 interferonopathies in which the cause of the disease is a variation in the RNASEH2C gene.
Homologues: Orthologues: chimpanzee RNASEH2C (95% identical), macaque RNASEH2C (95% identical), pig RNASEH2C (75% identical), dog RNASEH2C (74% identical), mouse Rnaseh2c (65% identical), guinea pig RNASEH2C (64% identical), rat Rnaseh2c (62% identical).
Diseases named in the same sentence as RNASEH2C in open-access papers:
RNASEH2C is named in the same sentence as 20 diseases in open-access papers, as found by Europe PMC text mining. Sharing a sentence is not in itself a finding about the gene and the disease. The quoted sentences say what the papers report.
Aicardi-Goutières syndrome (11 papers, 2016 to 2025). "Further, mutations in some of the genes have been associated with neurological phenotypes, such as Aicardi-Goutierès syndrome (RNASEH2C), intellectual disabilities and epilepsy (DNM1), and autism spectrum disorder (ARRB2)." (PMID 37147306, 2023). "Aicardi-Goutieres syndrome (AGS) is an early-onset encephalopathy that can be caused by a gene mutation in one of 7 discovered genes so far (TREX1, RNASEH2B, RNASEH2C, RNASEH2A, SAMHD1, ADAR1, and IFIH1)." (PMID 32737687, 2020). "In the severe neuroinflammatory disorder Aicardi-Goutières syndrome, more than 50% of total AGS patients have biallelic mutations in one of the three genes encoding RNase H2: 5% for RNASEH2A, 36% for RNASEH2B, and 12% for RNASEH2C." (PMID 32069311, 2020). "The genetic dissection of a particular type I interferonopathy, Aicardi-Goutières syndrome, initially described as an early-onset progressive brain disease, identified mutations of the TREX1, RNASEH2A, RNASEH2B, RNASEH2C, SAMHD1, ADAR, and MDA5 genes as causal." (PMID 27190218, 2016). "Aicardi-Goutieres syndrome is classified as a monogenic interferon disease resulting from an aberrant mechanism involving intracellular nucleic acid sensing mediated by TREX1, RNASEH2A, RNASEH2B, RNASEH2C, SAMHD1, ADAR1 or IFIH1." (PMID 39286150, 2024).
breast carcinoma (3 papers, 2019 to 2022). "RNASEH2C was reported as a metastasis susceptibility gene and modulator of T cell-mediated immune response in breast cancer." (PMID 36147313, 2022). "Such a mechanism has been suggested for RNASEH2C as a metastasis susceptibility gene in breast cancer." (PMID 33353557, 2020). "Together these data indicate that Rnaseh2c expression contributes to a patient’s susceptibility to developing breast cancer metastasis and demonstrate that the immune system is involved in this outcome." (PMID 31125342, 2019). "In summary, the results from our study implicate Rnaseh2c as a metastasis susceptibility gene that influences breast cancer metastasis through a novel, potentially enzyme-independent mechanism that involves cytotoxic T cells." (PMID 31125342, 2019). "To verify Rnaseh2c’s role as a bona fide metastasis modifier, we knocked down Rnaseh2c in a second mouse metastatic mammary cancer cell line, 4T1." (PMID 31125342, 2019).
asthma (1 paper, 2018). "There were common genes between these two study groups, where five genes were up-regulated (ATP5E, BRK1, KCNJ6, RNASEH2C, and RPL9) and one gene (RAB5B) was down-regulated in patients with mild and severe asthma compared with normal individuals." (PMID 30038057, 2018).
autoimmune disease (1 paper, 2025). A disorder resulting from loss of function or tissue destruction of an organ or multiple organs, arising from humoral or cellular immune responses of the individual to their own tissue constituents. "Although RNASEH2C is linked to autoimmune diseases, its role in tumor immunity is less understood." (PMID 41361104, 2025).
Cerebral atrophy (1 paper, 2021). Atrophy (wasting, decrease in size of cells or tissue) affecting the cerebrum. "Aicardi-Goutières (AGS) is a rare immune dysregulated disease due to mutations in TREX1, RNASEH2A, RNASEH2B, RNASEH2C, SAMHD1, ADAR1 or IFIH1, characterized by encephalopathy, dystonia, basal ganglia calcifications, white matter abnormalities, and cerebral atrophy." (PMID 33482855, 2021).
colorectal cancer (1 paper, 2019). A primary or metastatic malignant neoplasm that affects the colon or rectum. "In colorectal cancer, RNASEH2C mRNA was found to be reduced in tumor tissue compared to normal, while increased expression of RNASEH2B and RNASEH2C was correlated with metastasis, like in our study." (PMID 31125342, 2019).
hepatocellular carcinoma (1 paper, 2025). A malignant tumor that arises from hepatocytes. "This study explored how Rnaseh2c+ macrophages influence hepatocellular carcinoma (HCC) progression using in vitro cell models and mouse tumor models." (PMID 41361104, 2025).
Infertility (1 paper, 2021). "Other major DEPs, including RNASEH2C, TAPBPL, TUBB8, NFRKB, MASTL, and MYLK, have never been reported to be associated with infertility, metabolic disorders, or hormone imbalances." (PMID 34016141, 2021).
liver fibrosis (1 paper, 2019). "Results of eQTL analysis indicated that different genotypes of rs7101916 could cause differential mRNA level of ribonuclease H2 subunit C (RNASEH2C) in transformed fibroblasts cells and influence liver fibrosis process after HCV infection." (PMID 31346215, 2019).
lupus (1 paper, 2022). "The rationale for selecting SLE is twofold: some SLE risk alleles act to augment the interferon response (e.g. IRF5, IRF7, CXORF21-TASL); other lupus susceptibility genes act in the intracellular viral sensing (e.g. IFIH1, TLR7, RNASEH2C) pathway." (PMID 36327221, 2022).
metastatic disease (1 paper, 2019). "The results from our study reveal a role for the immune system in limiting Rnaseh2c-mediated metastatic disease which involves the cytotoxic T cell response." (PMID 31125342, 2019). "We found that the role of Rnaseh2c in metastatic disease is independent of RNase H2 enzymatic activity, and immunophenotyping and RNA-sequencing analysis revealed engagement of the T cell-mediated adaptive immune response." (PMID 31125342, 2019).
microcephaly (1 paper, 2020). A congenital or acquired developmental disorder in which the circumference of the head is smaller than normal for the person's age and sex. "AGS caused by mutations in TREX1, RNASEH2A, and RNASEH2C usually presents early in the neonatal period as “pseudo-TORCH” manifestations with severe neurological dysfunction in the form of progressive microcephaly, spasticity, psychomotor retardation, and may lead to death." (PMID 32737687, 2020).
tumor (3 papers, 2019 to 2025). "Our study found that in HCC, RNASEH2C promoted tumor progression by inhibiting tumor-associated antigen presentation, weakening the adaptive immune response and worsening HCC progression." (PMID 41361104, 2025). "Our research has thus far concentrated solely on the role of RAI14, leaving the involvement of PRDX1 in RNASEH2C-mediated tumor regulation unclear." (PMID 41361104, 2025). "To identify the tumor-modulating role of Rnaseh2c+ macrophages, we conditionally knocked Rnaseh2c out on macrophages and found Rnaseh2c-cKO significantly inhibited tumor growth and extended survival compared to controls." (PMID 41361104, 2025). "In this study, we found that changing the expression of the gene Rnaseh2c changed the number of metastases that developed in the lungs of tumor-bearing mice." (PMID 31125342, 2019). "Thus, RNASEH2C advanced tumor progression by promoting RAI14 lysosomal degradation, with HSC70 and CMTM6 playing key roles." (PMID 41361104, 2025). "Clarifying the role of RNASEH2C in tumor cells was also of critical importance." (PMID 41361104, 2025). "Our investigation into the effects of RNASEH2C on HCC cells revealed that neither knockout nor overexpression of Rnaseh2c in Hep-53.4 cells influenced tumor growth." (PMID 41361104, 2025). "This indicated that reduction of Rnaseh2c expression in tumor cells did not affect metastatic colonization after a bolus injection into the venous circulation." (PMID 31125342, 2019). "The additional in vivo evidence further confirms that the effect of Rnaseh2c expression on metastasis is not primarily through altering tumor growth." (PMID 31125342, 2019). "Additionally, Rnaseh2c+ macrophages, identified as non-classically polarized, mainly promote tumor growth by inhibiting antigen presentation." (PMID 41361104, 2025). "This suggested RNASEH2C’s pro-tumor effects were independent of M2 macrophages." (PMID 41361104, 2025).
cancer (2 papers, 2018 to 2025). A tumor composed of atypical neoplastic, often pleomorphic cells that invade other tissues. "We first screened the messenger RNA (mRNA) expression of the nucleotide degrading enzyme genes TREX1, SAMHD1, RNASEH2A, RNASEH2B, and RNASEH2C in 14 cancer types using TCGA RNAseq data." (PMID 29843367, 2018).
RNASEH2C also shares sentences with these, for which no sentence is quoted: ovarian carcinoma (2 papers); autism spectrum disorder (1); brain disease (1); complement deficiencies (1); Encephalopathy (1); metabolic disorders (1).